TNFRSF18 (TNF receptor superfamily member 18)
Diseases named in the same sentence as TNFRSF18 in open-access papers (continued):
Sharing a sentence is not in itself a finding about the gene and the disease.
tumor (345 papers, 2006 to 2026). "Single-cell RNA-sequencing revealed ALDH dysregulation associates with a suppressive tumor microenvironment, marked by Tregs infiltration and TNFRSF18 upregulation." (PMID 38725845, 2024). "C12_CD4, which mainly comprised CD4+ T cells from tumors, was associated with high gene accessibility for markers of tumor-infiltrating regulatory T cells (Tregs), including TNFRSF18, ICOS and CTLA4." (PMID 35668194, 2022). "Knockout of TNFRSF18 is associated with changes in the immune tumor microenvironment and cytokine secretion." (PMID 34367975, 2021). "Importantly, several studies have found that TNFRSF18 is a marker of Tregs and is associated with Treg activation in both human and murine models 20, 21, suggesting its potential as a target for anti-tumor immunotherapy." (PMID 38725845, 2024). "One of TNFRSFs, TNFRSF18 (GITR), a recently identified novel tumor suppressor on chromosome 1p36, loss of which might be highly related to pathogenesis in differential human cancers." (PMID 25973846, 2015). "TNFRSF18 expression was notably higher in T cells infiltrating tumour tissues relative to their counterparts in adjacent non‐tumorous areas, with high‐expressing CD8+ T cells exhibiting marked exhaustion features." (PMID 40770837, 2025). "Particularly noteworthy is the robust positive correlation between TIGD1 and HMGB1 expression across nearly all tumor types, along with significant associations with ICAM1, CCL5, and TNFRSF18 in the majority of cancers." (PMID 40565566, 2025). "The high expression of TNFRSF18 in early‐stage (T2) tumours suggests its potential to be a preliminary biomarker for screening of CRC." (PMID 40770837, 2025). "GITR (TNFRSF18) stimulation can reinvigorate exhausted tumor-infiltrating lymphocytes, particularly when combined with anti-PD-1 therapy." (PMID 40236693, 2025). "As a novel immune checkpoint, TNFRSF18 is expressed on the surface of tumor cells and leads to immune escape." (PMID 40535819, 2025). "Compared with TNFRSF18+ T cells, TNFRSF18− T cells exhibited stronger cytotoxic activity against tumour cells within the TNF signalling pathway." (PMID 40770837, 2025). "Compared to Treg.1, Treg. showed significantly up-regulated genes (TNFRSF4/OX40, TNFRSF18/GITR, TNFRSF9/4–1BB, TNFRSF1B/TNFR2 and LAIR2) associated with suppressive functions of tumor-infiltrating Tregs49." (PMID 39803458, 2025). "The KLF4-assocaited genes that were least correlated with a tumor stimulatory effect for several tumors included TNFRSF18." (PMID 40299916, 2025). "Emerging evidence suggests that TNFRSF18-expressing Tregs represent a major immunosuppressive population of immune cells in many tumor types 44-46." (PMID 38725845, 2024). "Costimulatory molecules ICOS, TNFRSF4, and TNFRSF18 are expressed on the surface of tumor-infiltrated Tregs and favor suppressive function of Tregs." (PMID 38358826, 2024). "Here, we discovered a key regulator in inflammatory and immune response factor, TNFRSF18 (GITR), that was constitutively highly expressed in the T&NK cells of tumor tissues than normal tissues." (PMID 37488117, 2023). "The CD8+ T cells, the inflammation-promoting function, the high immunity score, the activation of CD27, LAG3, and TNFRSF18, played a critical role in the hot tumour." (PMID 35937987, 2022). "CD4+LAIR2+ cells highly expressed Treg cell lineage markers, including IL2RA, CTLA4, TNFRSF18, ICOS, TIGIT, and tumor-associated Treg cell marker CCR8, consistent with CD4+ LAIR2+ cells being of Treg lineage and not recently activated T cells." (PMID 35008369, 2021). "Other genes identified in this study as over-expressed in CIN3/AIS lesions compared to normal cervical tissue are also associated with tumor development (KRT7, TNFRSF18 and TNFRSF4)." (PMID 35008799, 2021).
tumor (continued). "Multiple preclinical studies have provided evidence that stimulation of GITR (TNFRSF18) in the tumor microenvironment contributes to costimulatory activation of CD4 and CD8 T-cells, while inhibiting/depleting intra-tumoral regulatory T cells." (PMID 32767058, 2021). "Both CD4_5 and CD4_7 had expression of regulatory T (Tregs) cell markers, with higher levels of FOXP3, IL2RA (CD25), CTLA4, and TNFRSF18 (GITR) in the tumor-predominant CD4_5." (PMID 33504936, 2021). "CXCL5, ELN, JUN, and FGFR4 were highly expressed in normal tissues, while PLAU, RNASE7, JAG1, SPP1, and TNFRSF18 were highly expressed in tumor tissues." (PMID 32699529, 2020). "Comparing all these studies has yielded a common set of genes such as CTLA4, TNFRSF4, TNFRSF18, TIGIT, ICOS, and CCR8 whose expression is higher in tumor‐associated Treg cells as compared to Treg cells from other tissues." (PMID 32272497, 2020). "The higher expression of PD-L2 or TNFRSF18 was significantly associated with good survival outcome in LIHC or BRCA/HNSC cancer patients, respectively, after adjusting for the abundances of tumor infiltrating immune cells." (PMID 31358815, 2019). "TNFRSF18 is also known as GITR, which functions as an important costimulatory molecule that enhances anti-tumor actions of effector T cells." (PMID 31358815, 2019). "Cell line screening showed the enrichment of cancer cells deprived of the expression of CD27, CEACAM1, CTLA4, LRIG1, PDCD1LG2, or TNFRSF18, suggesting their role as tumor suppressor." (PMID 31358815, 2019). "Among the overexpressed genes, PTGDS (13.761-fold) had the highest log2 fold change in tumor versus non-tumor tissues, followed by TNFRSF18 (13.387-fold), glial fibrillary acidic protein (GFAP) (12.296-fold), BARHL1 (12.175-fold), and KIF26A (11.719-fold)." (PMID 30195786, 2018). "Additionally, higher levels of Treg cells were found in the primary tumor tissue, expressing elevated levels of costimulatory genes associated with immune checkpoints (CD27, ICOS, TNFRSF4, and TNFRSF18) and exhaustion markers (CTLA4 and TIGIT)." (PMID 40303346, 2025). "Simultaneously, the majority of traditional immune checkpoints, such as TNFRSF18, are also upregulated, which might inhibit the clearance of tumor cells by these cytotoxic cells." (PMID 38605343, 2024). "Among them, CTLA4, TIGIT, TNFRSF4 and TNFRSF18 were highly expressed in tumor-infiltrating Tregs." (PMID 35562760, 2022). "In agreement with our flow cytometry results, we identified a significant upregulation in several genes encoding for immune checkpoint inhibitory molecules (e.g. Pdcd1, Lag3, Ctla4, Icos, Tigit, Tnfrsf18) in tumor-infiltrating CD4/ALK4-KO CD4+ T cells, compared to WT CD4+ T cells." (PMID 34548096, 2021). "Moreover, pTregs, generated in the tumor microenvironment, had reduced suppressive function and were hypermethylated in the Treg-related loci, e.g., Tnfrsf18 exon 5, compared to nTregs." (PMID 34281195, 2021). "Therefore, previous research showed that the roles of PD-L2 and TNFRSF18 are opposite in cancer immunity, with the former and the latter being coinhibitory and costimulatory molecules for anti-tumor T-cell responses, respectively." (PMID 31358815, 2019). "Moreover, immunofluorescence co‐localization analysis of patient‐derived CRC tumour sections revealed a significant spatial correlation (Pearson's r > .6) between TNFRSF18 and the canonical CD8+ T cell exhaustion marker TOX,43, 44, 45 exclusively within the tumour microenvironment." (PMID 40770837, 2025). "Mechanistically, TNFRSF18+ T cells are involved in immune regulation through the TNF signalling pathway, but TNFRSF18 expression decreased with tumour progression, suggesting that the tumour microenvironment may inhibit the apoptosis and immune activation function of exhausted T cells." (PMID 40770837, 2025).
tumor (continued). "Many downregulated genes in tumour‐infiltrating peripheral CD8+ T cells are associated with classical IFN responses (IFI6, IFI27, MX1, STAT1, EPSTI1 PARP9, ISG15), cell proliferation (STMN1, CENPF, HELLS, NUSAP1, and DNPH1), and T cell costimulation (CD28, TMIGD2, TNFRSF4, CD27, and TNFRSF18)." (PMID 39350478, 2024). "To validate whether expression of the three candidate genes (TNFSF4, TNFRSF18, and IL12RB2) in the tumor microenvironment is implicated in NK cell migration toward cancer cells, we conducted a Transwell migration assay using GBM U87MG cells, T cells, and NK cells derived from PBMCs." (PMID 36694264, 2023). "In addition, this study suggested that PDCD1LG2 (PD-L2) and TNFRSF18 could be the suppressor of tumor cells." (PMID 31358815, 2019). "This creates a feed‐forward loop: T cells expressing TNFRSF18 exhibited impaired TNF signalling, which compromised their ability to control highly stem‐like tumour cells and consequently accelerated immune evasion." (PMID 40770837, 2025). "TNFRSF18 expression impaired TNF signalling, weakening T cell cytotoxicity and enabling immune escape of ribosome‐rich tumour clusters." (PMID 40770837, 2025). "C0 TNFRSF18+ TCs were found in all three tissues, C1 DAPL1+ TCs and C4 MEIS2+ TCs were more common in both normal and tumor tissues overall, and C2 SLC40A1+ TCs were most common in one of the tumor samples." (PMID 40612060, 2025). "TNFRSF18 (GITR), in particular, exhibited broad expression within both invasive front and tumor core regions." (PMID 41057994, 2025). "Next, we examined the expression patterns of the 14 selected candidate genes and observed that only TNFRSF18 and CXCL13 were specifically expressed in tumour tissues and exhausted CD8+ T cells." (PMID 40770837, 2025). "Meanwhile, TNFRSF18− T cells have exhibited stronger immunoregulatory activity through the TNF pathway, while tumour cells with high stemness characteristics (high expression of RPS7/RPL30/RPL8) were more resistant to TNF‐mediated immunoregulation." (PMID 40770837, 2025). "In T cells, immune stimulation by the tumor led to the up-regulation of many co-stimulatory receptors, including ICOS, TNFRSF18, TNFRSF4, and TNFRSF9/4-1BB." (PMID 39475596, 2024). "Tumor necrosis factor receptor superfamily 18 (TNFRSF18, CD357), also known as GITR, is an important target for tumor immunotherapy." (PMID 37457707, 2023). "Meanwhile, we show the IHC staining of NRP1, HAVCR2, HHLA2CD44, TNFRSF18, TNFSF14, TNFRSF8, and CD276 in tumor tissues and normal tissues." (PMID 35685438, 2022). "Especially, TNFRSF18 (also known as glucocorticoid‐induced TNF receptor, GITR) was commonly expressed in both inflammatory and tumor areas." (PMID 35986392, 2022). "TNFRSF18 (also known as GITR) combines with the GITR ligand to favor T cell proliferation, and an anti-GITR antibody agonist (TRX518) displays potent anti-tumor activity." (PMID 34970594, 2021). "In terms of LUAD patients, most biomarkers, including IDO1, CTLA4, LAG3, CD40, TNFRSF18, TIGIT, and TNFSF14, were significantly increased in tumor tissues with high B cell abundance compared with that of low B cell group." (PMID 34422829, 2021). "Glucocorticoid-induced TNFR-related protein (GITR, TNFRSF18, CD357), a TNFR-SF member, is a co-stimulatory receptor that increases anti-tumor T cell activation." (PMID 30400822, 2018). "Ligation of co-stimulatory T cell receptors, such as OX40 (Tnfrsf4, CD134), 4-1BB (Tnfrsf9, CD137) and GITR (Tnfrsf18, CD357), with agonist mAbs has been shown to augment the anti-tumor immune response in numerous cancer models." (PMID 25411639, 2014). "During CRC progression, TNM‐stage‐driven remodelling of the tumour microenvironment (TME) induced progressive CD8+ T cell exhaustion marked by declining TNFRSF18 and rising CXCL13 expression in tumour‐infiltrating T cells elevation of both markers in the tumour compared with adjacent tissues." (PMID 40770837, 2025).
tumor (continued). "Specifically, the expression of TNFRSF18 gradually decreased with the advancing stage, whereas the expression of CXCL13 increased, suggesting they have a significant impact on T cell function and anti‐tumour immunity." (PMID 40770837, 2025). "Also important are TNFRSF17, TNFRSF18, TNFRSF4, members of the Tumor Necrosis Factor Receptor superfamily that bind to various TRAF family members and can regulate tumor cell proliferation and death." (PMID 39888956, 2025). "Moreover, the expression of ADAM10 was reciprocally exclusive with some tumor immune checkpoint genes, such as VEGFB, LAG3, IL4, TNFRSF18, TNFRSF4, TNF receptor superfamily member 14 (TNFRSF14), CD27, CCL5, etc.." (PMID 39211038, 2024). "Furthermore, TNFRSF18 expression was significantly upregulated in HCC patients with high ALDH activity, a marker of tumor-initiating cells." (PMID 38725845, 2024). "In conclusion, we identified TNFRSF18, TNFSF4, and IL12RB2 as biomarkers that predict response to NK cell therapeutics by studying the tumor immune microenvironment using NanoString and qRT-PCR analyses in patients with recurrent GBM who received activated NK cell treatment." (PMID 36694264, 2023). "Notably, genes of tumor necrosis factor receptor superfamily TNFRSF9, TNFRSF18, and TNFRSF4 were highly and exclusively expressed in the Tregs infiltrating the tumor." (PMID 36750562, 2023). "The results showed that m6Ascore was negatively correlated with the expression of TMIGD2, TNFRSF18, TNFRSF25, TNFRSF4, TNFRSF8, and NRP1, indicating that the poor prognosis of high-m6Ascore patients might be due to the tumor immunosuppressive microenvironment." (PMID 36313417, 2022). "Indeed, gene set enrichment and leading-edge analyses of activated, (shared) tissue, inflammatory and tumor-infiltrating Treg cell gene sets amongst others revealed sharing of the core eTreg cell genes, including BATF, CCND2, CCR8, TNFRSF18, and VDR." (PMID 33976194, 2021). "TNFRSF18 is involved in immune activation, promoting T cell proliferation and enhancing anti-tumor immune responses, while HHLA2 plays a role in immune checkpoint regulation, suppressing T cell activation and contributing to immune evasion in the tumor microenvironment." (PMID 38561648, 2024). "We identified TNFRSF18, TNFSF4, and IL12RB2 as biomarkers that predict response to NK cell therapeutics in recurrent GBM, which might provide a new treatment strategy for this highly aggressive tumor." (PMID 36694264, 2023). "We found that besides TNFRSF4, Treg functional signature genes such as FoxP3, CTLA4, TIGIT, TNFRSF18 (GIRT), CCR8, LAYN, and MAGEH1 were also overexpressed in C11-Tregs-FoxP3 of treatment-naive and non-MPR tumor lesions, but not for MPR tumor lesions." (PMID 35831283, 2022). "Similarly, a separate study presented a cuproptosis-related gene signature (involving TNFRSF18, SLC1A1, among others) to assess patient outcomes and the tumor immune environment, although it lacked clinical sample validation." (PMID 38326441, 2024).
cancer (133 papers, 2010 to 2026). A tumor composed of atypical neoplastic, often pleomorphic cells that invade other tissues. "Specifically, several immune checkpoints including TNFRSF18, TNFRSF4, VSIR, LGALS9, HAVCR2, and TNFRSF14 are significantly associated with RARA-AS1 in more than 10 types of cancer." (PMID 37833349, 2023). "Among the immunostimulatory factors, IL6R, TNFRSF18, TNFRSF25, and ULBP1 were significantly associated with RCC2 expression in the majority of cancer types." (PMID 36441563, 2022). "Glucocorticoid-induced tumor necrosis factor (TNF) receptor related gene or “GITR,” also known as TNF receptor superfamily member 18 (TNFRSF18), was listed by the National Cancer Institute as among the most promising immunotherapy agents for cancer." (PMID 29088720, 2017). "The expression profiles of cancer-related checkpoints showed that the majority of checkpoint-target genes had low expression levels in the high-risk group, and only TNFRSF25, TNFRSF4, TNFRSF14, TNFRSF18, and CD276 were upregulated in the high-risk group." (PMID 37190215, 2023). "TNFRSF18, also known as glucocorticoid-induced TNF receptor (GITR), a cell surface receptor expressed by immune cells (mainly Tregs), acts as a key regulator in inflammatory and immune responses and is an emerging molecular target in cancer immunotherapy." (PMID 37488117, 2023). "In addition, the analyses of forty-five immune stimulators showed that METTL1 expression was positively related to TNFRSF18 as well as negatively associated with TNFSF15 and IL6R in nearly all cancers." (PMID 35432338, 2022). "For instance, the expression of CD27, CTLA4, PDCD1LG2; TNFRSF18 were all significantly inhibited across different types of TCGA cancers as can be seen in the comprehensive study of more than 10,000 tumors comprising 33 diverse cancer types by utilizing data compiled by TCGA92." (PMID 31358815, 2019). "Subsequent analysis also demonstrated a clear relationship between GPX4 expression and key immune checkpoints such as VEGFB, TGFB1, CD276, TNFRSF18, and TNFRSF4 across most cancer types." (PMID 41142608, 2025). "They markedly expressed co-stimulatory molecules (e.g., TNFRSF4, TNFRSF9, TNFRSF18), adhesion, and IFN response signatures in the very late stage of cancer." (PMID 38645221, 2024). "The tumor necrosis factor receptor superfamily members 4 (TNFRSF4, OX40) and 18 (TNFRSF18, GITR, AITR) have been under investigation as potential targets for the immunotherapy of various cancers, including HNSCC." (PMID 37835379, 2023). "Based on an analysis of 30 human cancers, ATP7B expression was related to immunostimulatory activity, including ESCA(HHLA2:rho = 0.677, p < 2.2e-16; TNFRSF18:rho = -0.614, p < 2.2e-16)." (PMID 38037104, 2023). "On the other hand, the medium-expression group included TNFRSF18, TNFRSF4, CD27, and LAG3 and their expression levels varied significantly among the different cancer samples." (PMID 36157232, 2022). "TNFRSF18, also known as glucocorticoid-induced TNFR-related protein (GITR), is a costimulatory receptor in malignant tumors." (PMID 34660693, 2021). "Similarly, ZNF668 was positively correlated with PVRL2 (Nectin-2), CD276 (B7-H3), TGFB1, and multiple members of the TNF receptor superfamily, including TNFRSF4 (OX40), TNFRSF18 (GITR), and TNFRSF25, in the vast majority of analyzed cancers." (PMID 41614761, 2025). "ADM was found to exhibit a strong and consistent positive correlation with several immune checkpoint genes, including CD274 (PD-L1), CD276, TNFRSF18, TNFSF9, and PVR in the pan-cancer analysis, which contributed to the development of a suppressive immune microenvironment." (PMID 40529377, 2025). "Furthermore, the expression of GPX4 was closely associated with MHC molecules, immune activation genes, and immunosuppressive genes such as HLA-A, HLA-B, CD160, TNFRSF18, TNFRSF4 and CD276 in most cancer types." (PMID 41142608, 2025).